MIR513A2 (microRNA 513a-2)
Synonyms: hsa-mir-513-2; MIRN513-2; MIRN513A-2; MIRN513A2; hsa-mir-513a-2
Gene: MicroRNA gene on chromosome X (147,225,826 to 147,225,952, reverse strand). Ensembl gene ENSG00000207984.
Homologues: Orthologues: chimpanzee MIR513A-3 (100% identical), macaque mml-mir-513a-2 (61% identical), macaque mml-mir-513a-1 (61% identical), macaque mml-mir-513b-2 (59% identical), macaque mml-mir-513a-3 (58% identical), macaque mml-mir-513b-1 (57% identical), dog MIR507B (53% identical), rabbit ocu-mir-506 (28% identical), mouse Mir511 (27% identical). Paralogues in human: MIR506 (65% identical), MIR513B (61% identical), MIR507 (44% identical), MIR514A1 (43% identical), MIR514A2 (39% identical), MIR514A3 (39% identical), MIR509-1 (39% identical), MIR514B (37% identical), MIR509-3 (33% identical).